SATB1 (SATB homeobox 1)
Diseases named in the same sentence as SATB1 in open-access papers (continued):
Sharing a sentence is not in itself a finding about the gene and the disease.
gastric cancer (continued). "Concomitantly, SATB1 knockdown abrogated the HRG-promoted rescue of gastric cancer cells after MET inhibition." (PMID 33374770, 2020). "In line with this, SATB1 has been found to increase viability, invasiveness, and chemoresistance of gastric cancer cells and to promote tumor growth in vivo." (PMID 33374770, 2020). "In the present study, we demonstrate that treatment of MET-amplified gastric cancer cells with a MET inhibitor leads to a SATB1-mediated upregulation of HER3." (PMID 33374770, 2020). "The co-delivery of SATB1 shRNA and doxorubicin by using immunoliposomes was shown to have an antitumor effect on gastric cancer cells." (PMID 31450715, 2019). "In the past few years, several studies have shown the function of SATB1 as a prognostic biomarker in various types of cancers, such as breast, colorectal, pancreatic, and prostate cancer and other solid tumors, including gastric cancer." (PMID 31737131, 2019). "In our cohort of patients, HER2 and SATB1 were found to be overexpressed in gastric cancer tissue in comparison to normal gastric mucosa." (PMID 31737131, 2019). "In 2014, Peng and co-workers used a novel thermosensitive magnetic system based on liposomes to co-deliver doxorubicin and SATB1 shRNA into the gastric cancer cells." (PMID 31450715, 2019). "SATB1 was expressed in the nucleus of gastric cancer cells, and the positive rate was 30.77% (n = 32/104)." (PMID 31737131, 2019). "In conclusion, to the best of our knowledge, there are no reports which simultaneously analyzed the expression of HER2, NF-κB, and SATB1 proteins in patients with diagnosed gastric cancer." (PMID 31737131, 2019). "Over the past 10 years the role of SATB1 in cancer progression has been extensively studied in the most common human neoplasms, i.e., breast, colon, lung, prostate and stomach cancers, and it has been described in more than 150 papers." (PMID 31450715, 2019). "In the studied group, HER2 and SATB1 were found to be overexpressed in gastric cancer tissue in comparison to normal gastric mucosa." (PMID 31737131, 2019). "invasion and metastasis of GIN in Chinese patients correlates with SATB1 overexpression in tumor tissues, most profoundly in gastric cancer." (PMID 28636989, 2017). "SATB1 expression was also significantly more common in esophageal compared to cardiac or gastric cancer (p = 0.033)." (PMID 25326863, 2014). "In this study, we loaded doxorubicin and SATB1-shRNA vector into this system for the combination of gene therapy and chemotherapy, and evaluated their synergistic anti-tumor effect against gastric cancer in vitro and in vivo." (PMID 24675979, 2014). "In gastric cancer, SATB1 expression has been reported to correlate with a more malignant phenotype and poor prognosis whereas in squamous cell carcinoma of the lung, downregulation of SATB1 was demonstrated to be associated with an impaired survival." (PMID 22935204, 2012). "explored the relationship between SATB1, miR-495-3p, and lncRNA-UCA1, revealing that SATB1 knockdown in gastric cancer cells inhibited cell proliferation and invasion, induced apoptosis, and mirrored the effects of miR-495-3p overexpression and lncRNA-UCA1 suppression." (PMID 40071088, 2025). "Moreover, co-delivering DOX and SATB1 shRNA using a nanoparticle system notably inhibits gastric cancer growth." (PMID 40071088, 2025). "Interestingly, lncRNA-UCA1 knockdown reduced SATB1 expression in MKN-45 cells but not in BGC-823 cells, indicating a cell-dependent regulatory mechanism between lncRNA-UCA1 and SATB1 in gastric cancer." (PMID 40071088, 2025). "Thus, targeting SATB1 offers a promising strategy for overcoming drug resistance in gastric cancer, potentially enhancing the effectiveness of chemotherapy." (PMID 40071088, 2025).
gastric cancer (continued). "While in gastric cancer the role of SATB1 for the regulation of oncogene expression is still elusive, a meta-analysis has revealed that SATB1 expression itself represents a potential marker for unfavorable prognosis, emphasizing its putative relevance in this tumor type." (PMID 33374770, 2020). "The main aim of this research was the immunohistochemical assessment of the expression of the selected proteins, with a potential (NF-κB, SATB1) or proven (HER2) role in the pathogenesis of gastric cancer, both in the tumor tissue and in the normal gastric mucosa." (PMID 31737131, 2019). "Similarly, therapy utilizing SATB1 shRNA to eliminate gastric cancer stem cells is also being intensively developed." (PMID 31450715, 2019). "Aberrant expression of SATB-1 has been reported in cells of various cancer types, including prostate cancer, ovarian cancer, gastric cancer, hepatocellular carcinoma, renal cell carcinoma, rectal cancer, bladder cancer, laryngeal squamous cell carcinoma, and cutaneous malignant melanoma." (PMID 30337520, 2018). "The influence of SATB1 overexpression is more profound in gastric cancer patients." (PMID 28636989, 2017). "All these evidences suggested that SATB1 could be used to predict prognosis in gastric cancer patients." (PMID 28430598, 2017). "Moreover, the co-delivery of DOX and SATB1 shRNA exhibited enhanced activity to inhibit gastric cancer cell growth in vitro and in vivo, compared to single delivery." (PMID 24675979, 2014). "Our previous studies have shown that SATB1 plays an important role in gastric cancer, and may be an independent prognosis marker for gastric cancer." (PMID 24675979, 2014). "However, previous data suggest a role of SATB1 in the progression and metastasis of other tumor types, including non-small-cell lung cancer, gastric cancer and melanoma." (PMID 24932280, 2014). "Thus, we hypothesized that SATB1 could also be involved in HER-dependent resistance mechanisms upon MET inhibition in gastric cancer cells." (PMID 33374770, 2020). "This suggests that SATB1 may be a good marker for monitoring gastric cancer." (PMID 28636989, 2017). "Based on the successful construction of TSMCL, in this study we loaded DOX and SATB1 shRNA vector into TSMCL to make TSMCL-DOX-shSATB1 and evaluated the anti-tumor effects against gastric cancer cells in vitro and in vivo." (PMID 24675979, 2014). "Special AT-rich sequence binding protein 1 (SATB1) is a global genome organizer that has been demonstrated to promote aggressive tumor behavior in several different types of cancer, including gastric cancer." (PMID 25326863, 2014). "Notably, in the gastric cancer cells investigated here, SATB1 knockdown had no impact on the basal expression of any HER receptor; however, the upregulation of HER3 upon MET inhibition was prevented." (PMID 33374770, 2020).
prostate carcinoma (19 papers, 2013 to 2025). A carcinoma that arises from epithelial cells of the prostate gland. "SATB1 encodes a multipotent nuclear matrix-binding protein, which can promote the development of prostate cancer by regulating the epithelial–mesenchymal transition." (PMID 39590360, 2024). "Our findings prompted us to combine all risk factors with a strong impact on OS, namely SATB1 expression, degree of genomic instability and GS for a new Prostate Cancer Prediction Score (PCP-Score)." (PMID 34961766, 2021). "Additional studies on the loss-of-function models revealed that SATB1′s expression was required to maintain the invasive phenotype of prostate cancer cells." (PMID 31450715, 2019). "To investigate the role of SATB1 in the invasion of prostate cancer cells, we employed the loss of function approach to knockdown SATB1 expression in DU-145 cells in which SATB1 expression is relatively high." (PMID 23642278, 2013). "Overexpression of chromatin organizing SATB1 has been widely studied to be associated with growth, metastatic potential, progression, poor survival and co-expression of multiple oncogenes in multiple cancer types including prostate cancer." (PMID 36809527, 2023). "Therefore, both gain and loss of function approaches demonstrate that SATB1 promotes prostate cancer cell invasion and proliferation in vitro, and these results are consistent with the data on the clinical prostate cancer samples." (PMID 23642278, 2013). "In conclusion, we demonstrated that our Score containing SATB1 expression, examined by immunohistochemical analysis in a multiple sample approach, combined with genomic instability and GS is a predictor for prognosis in prostate cancer potentially outperforming risk stratifications in current use." (PMID 34961766, 2021). "In prostate cancer cell lines (PC-3M, DU-145, and LNCaP), SATB1 knockdown markedly reduces cell proliferation, invasion, and growth." (PMID 40071088, 2025). "Further research supports the critical role of SATB1 in maintaining the invasive potential of prostate cancer cells." (PMID 40071088, 2025). "Overall, SATB1 consistently emerges as a promoter of proliferation, invasion, and migration in prostate cancer, while its downregulation triggers nuclear consolidation and apoptosis, particularly in DU-145 cells." (PMID 40071088, 2025). "In this context, differences in protein expression (SATB1, SPIN1, TBB5, VIME, TPM4) between benign prostate tissue and prostate cancer with respect to clinicopathological risk factors, tumor heterogeneity and genomic instability were assessed." (PMID 34961766, 2021). "The cell culture studies revealed an elevated SATB1 expression in prostate cancer cell lines compared to normal prostate epithelial cells." (PMID 31450715, 2019). "Although there are only seven studies concerning SATB1′s expression in prostate cancer, they consistently show its role as a metastasis-promoting factor in this type of tumour." (PMID 31450715, 2019). "The results of these studies strongly suggested an important role of SATB1′s expression in the progression of prostate cancer." (PMID 31450715, 2019). "SATB1′s knockdown in prostate cancer cell lines (DU-145, PC-3M and LNCaP) significantly inhibited cell growth, proliferation and invasion rates." (PMID 31450715, 2019). "Here we show that a four-gene signature based on HBEGF, HOXC13, IGFBP2, and SATB1 was able to identify patients whose prostate cancer recurred." (PMID 27966447, 2017). "Publicly available microarray data indicates that SATB1 is downregulated in prostate cancer as well as other solid tumors." (PMID 27966447, 2017). "Increased nuclear localization of SATB1 has been reported to be correlated with increased prostate cancer aggression and invasive potential." (PMID 27966447, 2017).
prostate carcinoma (continued). "In our future investigations, we will examine the expression of these important SATB1 targets in prostate cancer cells, to provide novel insights into the potential oncogenic role of SATB1 in prostate cancer." (PMID 23642278, 2013). "Collectively, these results suggest that silencing of SATB1 inhibits the invasion and growth of prostate cancer cells." (PMID 23642278, 2013). "Taken together, these results suggest that SATB1 promotes the invasion and growth of prostate cancer cells." (PMID 23642278, 2013). "SATB1 expression is positively correlated with the bone metastasis and the Gleason score of prostatic carcinoma." (PMID 23642278, 2013). "To provide further evidence that SATB1 contributes to prostate cancer development, we employed several prostate cancer cell lines LNCaP, DU-145 and PC-3, and performed gain and loss of function experiments." (PMID 23642278, 2013). "SATB1 overexpression promotes prostate cancer cell proliferation and invasion while SATB1 knockdown inhibits prostate cancer cell proliferation and invasion." (PMID 23642278, 2013). "LNCaP, DU-145, and PC3 prostate cancer cells were examined for SATB1 expression by Western blot analysis." (PMID 23642278, 2013). "To further confirm the role of SATB1 in the invasion of prostate cancer cells, we employed the gain of function approach to overexpress SATB1 in LNCaP cells in which SATB1 expression is relatively low." (PMID 23642278, 2013). "In this study, we performed immunohistochemistry analysis to examine the expression of SATB1 in clinical prostatic carcinoma samples and analyze the correlation of SATB1 expression with the clinicopathological features of prostate cancer." (PMID 23642278, 2013). "The results showed that the positive rate of SATB-1 staining was 86.7% (104/120) in 120 cases of prostatic carcinoma and 0% (0/60) in 60 cases of benign prostate hyperplasia." (PMID 23642278, 2013). "SATB1 has been identified as a key player in prostate cancer metastasis." (PMID 40071088, 2025). "Silencing SATB1 exhibits strong inhibitory effect on the growth of prostate cancer." (PMID 33613773, 2021). "Most notably, the parameters SATB1 (when assessed by multiple samples from different tumor sites), pathological GS and genomic instability could be combined as a new Prostate Cancer Prediction Score (PCP-Score) which is a significant predictor for OS." (PMID 34961766, 2021). "From that gene set we chose two genes, SATB1 and LMNA, for further assessment as potential biomarkers of high-risk prostate cancer because both genes repositioned in a single high-risk T3 stage cancer, but not in two intermediate risk T2 cancers, or a low risk T2 cancer." (PMID 31681438, 2019). "Similarly, transfection with SATB1 expression plasmids was also shown to increase proliferation, migration, and the invasion capabilities of different prostate cancer cell lines." (PMID 31450715, 2019). "SATB1 expression in prostate cancer tissues was examined by immunohistochemistry." (PMID 23642278, 2013). "In addition, SATB1 staining was stronger in cells of prostatic carcinoma with metastasis than in those of prostatic carcinoma without metastasis." (PMID 23642278, 2013). "Furthermore, we analyzed the correlation of SATB1 expression with clinicopathological features of prostate cancer." (PMID 23642278, 2013). "Based on these results, we speculated that SATB1 expression is correlated with the invasion ability of prostate cancer cells." (PMID 23642278, 2013). "However, further studies are important to investigate the molecular mechanisms by which SATB1 promotes the malignant behaviors of prostate cancer cells." (PMID 23642278, 2013). "In this study we first examined the expression of SATB1 in clinical prostate cancer tissues." (PMID 23642278, 2013). "However, the functional role of SATB1 in prostate cancer progression and metastasis remains elusive." (PMID 23642278, 2013).
prostate carcinoma (continued). "Thus we speculate that SATB1 modulates gene expression to regulate the proliferation and invasion of prostate cancer cells." (PMID 23642278, 2013). "In addition, a very recent study showed that knockdown of SATB1 in highly aggressive prostate cancer PC-3 M cells inhibited tumor growth and invasion along with increased E-cadherin expression, suggesting that SATB1 promotes prostate cancer aggressiveness through epithelial-mesenchymal transition." (PMID 23642278, 2013). "Since SATB1 expression is positively correlated with the bone metastasis of prostate cancer, we hypothesized that SATB1 expression may confer high invasion ability in prostate cancer cells." (PMID 23642278, 2013). "Conversely, SATB1 overexpression in LNCaP cells promotes xenograft tumor growth and induces EMT-related protein expression, further enhancing prostate cancer cell proliferation, invasion, and migration." (PMID 40071088, 2025). "The SATB1 gene can contribute to tumor growth in a mammary adenocarcinoma mouse model, while ZNF507 was reported to affect TGF-β signaling to promote prostate cancer." (PMID 35625741, 2022). "The differentially expressed gene-list contained various genes previously reported to be differentially expressed in low- and intermediate/high-grade prostate cancer such as HOXC6, MAGEC2, HERPUD1 and SATB1." (PMID 27191985, 2016). "First, FOXP3 represses expression of the HER2, Skp2, SATB1 and MYC oncogenes, and induces expression of the tumor suppressor genes p21 and LATS2 in breast and prostate cancer cells." (PMID 24406338, 2014). "However, the expression and role of SATB1 in prostate cancer remain unclear." (PMID 23642278, 2013). "Therefore, we speculate that during prostate cancer metastasis the downregulation of miR-448 may contribute to the upregulation of SATB1, which may explain our observation that SATB1 expression was positively correlated with the bone metastasis of prostate cancer." (PMID 23642278, 2013). "In this study, we constructed oncolytic adenovirus carrying SATB1 named as Ad-ZD55-SATB1 (ZD55-SATB1) and combined it with chemotherapeutic drug DTX to explore the effects on proliferation, invasion, and apoptosis of prostate cancer cells in vitro and in vivo." (PMID 33613773, 2021). "Despite their tumor biology functions, neither SATB1, SPIN1, VIME, TBB5 nor TPM4 are yet being used in routine risk assessment for prostate cancer." (PMID 34961766, 2021). "Similarly, LMNA repositioned in 36.4% (4/11), SATB1 in 34.8% (8/23), and TGFB3 in 31.8% (7/22) of prostate cancer tissues." (PMID 31681438, 2019). "LMNA and SATB1 positioning patterns were not able to stratify prostate cancers by Gleason score and SP100, TGFB3 and SATB1 were not accurate markers of risk or aggressiveness of the cancer." (PMID 31681438, 2019). "Positioning patterns for SATB1 and LMNA by prostate cancer subgroups." (PMID 31681438, 2019). "FOXP3 has been shown to exert its growth inhibitory effect on breast and prostate cancer cells by transcriptionally repressing the expression of specific oncogenes (HER2, SKP2, SATB1 and MYC), and inducing the expression of specific tumor suppressor genes (CDKN1A, LATS2)." (PMID 24406338, 2014). "Furthermore, we used a panel of prostate cancer cell lines including LNCaP, DU145, and PC3 to investigate the function of SATB1 in prostate cancer cell proliferation and invasion." (PMID 23642278, 2013). "SATB1 staining was stronger in prostatic carcinomas with metastasis than in those without metastasis, but was absent in benign prostate hyperplasia." (PMID 23642278, 2013). "SATB1 was not stained in cells of benign prostate hyperplasia, but was positively stained in the nucleus of prostate cancer cells." (PMID 23642278, 2013). "The immunohistochemistry analysis showed that SATB1 staining was stronger in prostatic carcinoma with metastasis than in prostatic carcinoma without metastasis, but was absent in benign benign prostate hyperplasia." (PMID 23642278, 2013).
prostate carcinoma (continued). "To determine whether SATB1-derived peptide-specific T cells were able to recognize and kill HLA-A*02+, SATB1-expressing cancer cells, we used an HLA-A*02− SATB1 mRNA positive prostate cancer cell line PC3 (as a negative control) and five HLA-A*02+ SATB1 mRNA positive cancer cell lines." (PMID 23437226, 2013). "We show that systemic dysregulation of CRGs is also found in prostate cancer, including a 4-gene signature (HBEGF, HOXC13, IGFBP2, and SATB1) capable of differentiating recurrent from non-recurrent prostate cancer." (PMID 27966447, 2017).